KRT6A (keratin 6A)
Diseases named in the same sentence as KRT6A in open-access papers (continued):
Sharing a sentence is not in itself a finding about the gene and the disease.
psoriasis (17 papers, 2018 to 2026). An autoimmune condition characterized by red, well-delineated plaques with silvery scales that are usually on the extensor surfaces and scalp. "Histopathological changes were assessed using hematoxylin and eosin staining, while molecular alterations were examined by RT-qPCR analysis of psoriasis-associated keratin genes (Krt16, Krt17, and Krt6a) and evaluation of JAK-STAT signaling activity." (PMID 41976231, 2026). "KRT6A is a hallmark of psoriasis, a disease resulting from ectopic proliferation and dysregulated differentiation of KCs." (PMID 39782692, 2025). "Krt6a is implicated in psoriasis pathogenesis and is associated with the wound healing/regenerative phenotype seen in psoriasis." (PMID 32597759, 2020). "KRT6A knockdown rescued the disease-associated downregulation of these molecules in rosacea and psoriasis mouse models, suggesting that KRT6A may contribute to skin inflammation by modulating barrier function." (PMID 40346694, 2025). "We demonstrate that KRT6A is significantly overexpressed in the epidermis of rosacea and psoriasis lesions." (PMID 40346694, 2025). "In this study, we found that KRT6A expression was upregulated in the epidermis of both rosacea and psoriasis." (PMID 40346694, 2025). "IF staining confirmed efficient knockdown of KRT6A, which significantly improved psoriasis-like pathology, including acanthosis and inflammatory leukocyte infiltration." (PMID 40346694, 2025). "Consistent with our observations in rosacea, KRT6A overexpression exacerbated psoriasis-like phenotypic and histological changes, including enhanced epidermal thickening and inflammatory cell infiltration." (PMID 40346694, 2025). "KRT6A expression was elevated in lesional skin from patients and mouse models of rosacea and psoriasis." (PMID 40346694, 2025). "To further validate these findings, we assessed the effects of KRT6A overexpression in IMQ-induced psoriasis-like mice." (PMID 40346694, 2025). "In mice with LL37-induced rosacea-like and imiquimod (IMQ)-induced psoriasis-like skin inflammation, KRT6A knockdown alleviated inflammation, whereas KRT6A overexpression exacerbated inflammatory responses." (PMID 40346694, 2025). "Collectively, these results indicate that epidermal KRT6A promotes the pathogenesis of inflammatory skin diseases, including rosacea and psoriasis, highlighting its potential role as a therapeutic target." (PMID 40346694, 2025). "KRT6A upregulation was also observed in psoriasis lesions and IMQ-induced psoriasis-like mouse models, where its expression was localized primarily to epidermal keratinocytes." (PMID 40346694, 2025). "Given that multiple signaling pathways contribute to the pathogenesis of rosacea and psoriasis, we investigated the downstream mechanisms of KRT6A by examining changes in these pathways following KRT6A knockdown via siRNA in HaCaT keratinocytes." (PMID 40346694, 2025). "Functionally, KRT6A knockdown alleviates skin inflammation in mouse models of rosacea and psoriasis, whereas lentivirus-mediated KRT6A overexpression exacerbates inflammatory responses." (PMID 40346694, 2025). "Collectively, these findings suggest that targeting epidermal KRT6A alleviates inflammation in rosacea and psoriasis, highlighting its potential as a therapeutic target for inflammatory skin diseases." (PMID 40346694, 2025). "To extend these findings to psoriasis, we evaluated the effects of KRT6A knockdown in an IMQ-induced psoriasis-like mouse model." (PMID 40346694, 2025). "Moreover, KRT6A knockdown alleviated, while its overexpression exacerbated, rosacea-like and psoriasis-like phenotypes in mice." (PMID 40346694, 2025). "KRT6A was expressed in lesional interfollicular skin in Spink5 cKO mice, consistent with the known upregulation of KRT6A expression in interfollicular keratinocytes upon trauma, wounding or hyperproliferative skin diseases such as psoriasis." (PMID 38316920, 2024).
psoriasis (continued). "Further psoriasis and AD share the KRT6A, KRT6B, KRT6C, KRT16, KRT17 as their common DEGs." (PMID 35874668, 2022). "In conclusion, NB-UVB normalizes psoriatic plaques by suppressing the expression of psoriasis signature genes, such as IL36G, DEFB4A/B, S100A15, SERPINB4, KRT16, and KRT6A in, both, the PE and CE skin." (PMID 36928592, 2023). "The core NB-UVB downregulated DEGs included a few psoriasis signature genes, such as IL36G, DEFB4A/B (coding human β defensin 2), S100A15, SERPINB4, KRT16, KRT6A, and DSC220." (PMID 36928592, 2023). "A series of psoriasis-related genes, such as S100A8, S100A9, KRT6A (keratin 6A), KRT6B, KRT6C, KRT16, and MMP9 (metalloproteinase 9), were also down-regulated." (PMID 35273606, 2022). "Additionally, NB‐UVB modulates the oxidative stress response and results in suppression of psoriasis signature gene expression (e.g., IL 36G, DEF4A/B, S100A15, KRT16, and KRT6A)." (PMID 40908513, 2025). "Four of the top six keratins (Krt16, Krt17, and Krt6a and b) that were increased in mice lacking epidermal Pparg are keratins that are known to serve as alarmins and are up-regulated in wound healing and psoriasis." (PMID 34445339, 2021).
bladder cancer (10 papers, 2008 to 2024). "The association of keratin 6a and squamous differentiation is given further significance, as there is evidence that squamous differentiation in patients with bladder cancer is associated with a more aggressive cancer and a poor prognosis." (PMID 18414623, 2008). "Several of the individual genes upregulated by Gardnerella exposures are involved in epithelial to mesenchymal transition (Cxcl5, Cxcr2, Tff1) or known to be elevated during squamous metaplasia or bladder cancer (Anxa10, Fosl1, Krt6a, Mmp10)." (PMID 35782131, 2022). "High expression of basal keratins, such as KRT5 and KRT6A, is the most characteristic feature of the basal subtype of bladder cancer." (PMID 29956121, 2018). "The present studies show that keratin 6a is induced in UROtsa cells malignantly transformed by Cd2+ or As3+ and that keratin 6a overexpression also occurs in high-grade human bladder cancer." (PMID 18414623, 2008). "To determine if the findings in the UROtsa model system would translate to human bladder cancer, we performed keratin 6a staining on a small set of archival human bladder cancer specimens." (PMID 18414623, 2008). "Based on these scattered reports, one can hypothesize that keratin 6a overexpression in bladder cancer is a biomarker for malignant cells that have an activated growth factor pathway." (PMID 18414623, 2008). "There are several possibilities as to how keratin 6a expression might affect the development and progression of bladder cancer." (PMID 18414623, 2008). "The potential role that keratin 6a might play in the development and progression of bladder cancer is presently difficult to define because the keratin 6a gene has been only limitedly studied." (PMID 18414623, 2008). "The final aim was to demonstrate that the results from this model system could potentially translate to human disease by determining if keratin 6a was overexpressed in archival specimens of human bladder cancer." (PMID 18414623, 2008). "The other goals of the study were similarly reached when it was shown the keratin 6a was expressed in tumor heterotransplants generated from the Cd2+- and As3+-transformed cells and that keratin 6a was overexpressed in some archival patient specimens of high-grade bladder cancer." (PMID 18414623, 2008). "Our goals were to verify overexpression of keratin 6a in Cd2+- and As3+-transformed UROtsa cells, the corresponding tumor heterotransplants, and human bladder cancer biopsy specimens and to assess what factors may be involved in keratin 6a overexpression." (PMID 18414623, 2008). "We further illustrate this relationship with two well-described example markers of bladder cancer subtypes: FOXA1 and KRT6A." (PMID 36944729, 2023). "MiR-31-5p has been shown to exert tumor suppressive effects in bladder cancer by modulating downstream targets, including RAB27A and KRT6A." (PMID 36199571, 2022). "The same study found TRIM29 gene expression to be correlated to KRT5, KRT14, KRT6A, and KRT16 expression using The Cancer Genome Atlas (TCGA) RNA sequencing data from multiple tumor types, including basal subtype bladder cancers." (PMID 32822399, 2020). "Furthermore, in the TCGA bladder cancer data set, an increase correlation of TRIM29 was found with the basal genes P63, KRT5 and KRT6A suggesting a prominent role of these molecules in aggressive bladder cancers." (PMID 36293167, 2022). "Focal immunostaining of keratin 6a was also found in some but not all archival patient specimens of high-grade bladder cancer, confirming translation of the results to human bladder cancer." (PMID 18414623, 2008).
breast carcinoma (10 papers, 2013 to 2026). "Moreover, Krt6a expression is associated with basal phenotypes, a subtype that has poor clinical outcomes in breast cancer." (PMID 36933062, 2023). "The gene encoding KRT6A, which is located within the type II keratin gene cluster on human chromosome 12q, is closely associated with the prognosis and diagnosis of lung and breast cancers; however, few studies address its role in melanoma." (PMID 32934956, 2020). "To characterize the expression of AXL in vitro, we analyzed the expression of the tyrosine kinase, EMT (CDH1 and VIM), and basal (EGFR, KRT5, and KRT6A) markers in 15 breast cancer cell lines by quantitative real-time PCR (qRT-PCR)." (PMID 28721387, 2016). "Overexpression of KRT6A was significantly associated with worse DFS in younger patients with both basal and HER2-enriched breast cancer (p = 0.038, HR 2.85; p = 0.032, HR 3.6, respectively)." (PMID 25999348, 2015). "In human breast cancer patients, expression levels of KRT14 and KRT6A negatively correlated with expression of IGF1R." (PMID 42279332, 2026). "Overexpression of ANGPTL4 was associated with inferior outcome for young women with basal breast tumors; the same held true for the keratins (KRT5, KRT6A, and KRT6B) among young women with HER2-enriched breast cancer." (PMID 25999348, 2015). "This set comprised senescence markers (CDKN1A, LMNB1, MKI67), apoptosis regulators (BCL2, BCL2L1), a highly overexpressed gene (ITGB6), and drug targets (ACTA2, GSDMC, KRT6A, PDE1A, PSMA8), all of which showed strong concordance with our RNA-seq data in all four breast cancer cell lines." (PMID 40312750, 2025). "Moreover, the x43 cells represent a basal-like breast cancer as they express EGFR, Keratin 5 and Keratin 6A." (PMID 23593654, 2013).
nasopharyngeal carcinoma (7 papers, 2020 to 2024). A carcinoma arising from the nasopharyngeal epithelium. "Additionally, the increased KRT6A expression was observed in the nasopharyngeal carcinoma cell line, and it was noted that KRT6A silencing was associated with inhibition of cell invasion and metastasis formation via the β-catenin pathway." (PMID 39000463, 2024). "Downregulation of KRT6A expression can inhibit cell invasion and metastasis of nasopharyngeal carcinoma." (PMID 37081097, 2023). "KRT6A gene silencing has been shown to suppress cell viability, invasion, and metastasis of nasopharyngeal carcinoma via the β-catenin/TCF pathway." (PMID 35740697, 2022). "In one study, KRT6A silencing suppressed nasopharyngeal carcinoma cell invasion and metastasis via the β−catenin cascade." (PMID 35071014, 2021). "KRT6A is related to cell invasion and metastasis of nasopharyngeal carcinoma via the β-catenin cascade." (PMID 33221741, 2020). "Silencing KRT6A has been demonstrated to inhibit invasion and metastasis in nasopharyngeal cancers." (PMID 38612418, 2024). "Also, the KRT6A gene plays a critical role in epidermalization of squamous epithelium and in the EMT of nasopharyngeal carcinoma." (PMID 34795689, 2021).
pancreatic cancer (7 papers, 2021 to 2024). "Both KIF20A and KRT6A were reported to be highly expressed in tumor tissues and associated with poor prognosis in multiple cancers, such as prostate, breast, gastric and pancreatic cancers." (PMID 34249701, 2021). "Furthermore, in both lung and pancreatic cancer, up-regulation of KRT6A has been associated with an aggressive tumor phenotype and an adverse clinical outcome." (PMID 35884495, 2022). "The major molecular subtypes of pancreatic cancer, classical and basal-like (or quasi-mesenchymal), are represented in this single-cell transcriptome landscape as Ep_TRIM54 and Ep_KRT6A, respectively." (PMID 38297291, 2024). "KRT6A is a subtype of keratin highly upregulated in pancreatic cancer and predictive of patient survival." (PMID 34790815, 2021). "Studies have shown that IGF2BP3, ALB, KRT6A, and REG3 partake in the pancreatic cancer origin and development." (PMID 37505298, 2024). "Notably, we found that Ep_VGLL1 was spatially correlated with both Ep_TRIM54 and Ep_KRT6A whereas these two major populations representing classical and basal-like subtypes of pancreatic cancer, respectively, were not directly adjacent to each other." (PMID 38297291, 2024).
squamous cell carcinoma (7 papers, 2019 to 2025). A carcinoma arising from squamous epithelial cells. "Concretely, Epi2_MUC5B represented adenocarcinoma cell (MUC5B, MUC16, MUC5AC), while Epi4_MYC harbored conventional squamous cell carcinoma features, such as high expression of KRT6A and MYC." (PMID 40657372, 2025). "Another gene of interest, KRT6A, demonstrated significantly higher expression in squamous cell carcinoma compared to adenocarcinoma." (PMID 38612418, 2024). "The KRT6A protein is a potential biomarker for distinguishing LUAD from squamous cell carcinoma." (PMID 34060213, 2021). "By validating the expression profiles of six specific genes (MIR205HG, KRT5, KRT6A, KRT6C, SERPINB5, and DSG3), selected based on a previously established 53-gene signature, we consistently observed higher expression levels in squamous cell carcinoma (SCC) compared to adenocarcinoma (ADC)." (PMID 38612418, 2024). "This comparison showed an overlap of five genes (ETV4 (tumor non-malignant signature), STK32A, SPINK1, GOLT1A, KRT6A (adenocarcinomas—squamous cell carcinomas signature)) in the first case, and an overlap in one (KRT15) of the three most prominent genes in the second case." (PMID 36832225, 2023).
inflammatory skin disease (4 papers, 2011 to 2025). Inflammatory skin disorders covers a broad category that includes many conditions ranging in severity, from mild itching to grave medical health complications These disorders are common in people of all ages and races. "Targeting KRT6A may represent a novel therapeutic approach for inflammatory skin diseases associated with epidermal dysfunction." (PMID 40346694, 2025). "The spinous cluster also expressed KRT6A, KRT6C, and KRT16, which have been associated with inflammatory skin diseases and barrier dysfunction." (PMID 37675143, 2023).
bladder tumors (3 papers, 2018 to 2024). "In this current study, KRT6A transcript expression was shown to be expressed at very low levels in normal bladder tissue but was significantly elevated in bladder tumors, which confirms our previous results pertaining to KRT6A expression in the bladder." (PMID 39513911, 2024). "RAB27A and KRT6A promote proliferation and adhesion of bladder tumors and negatively correlate with miR-31-5p expression levels." (PMID 36199571, 2022).
melanoma (3 papers, 2021 to 2025). A malignant, usually aggressive tumor composed of atypical, neoplastic melanocytes. "We first found that KRT6A/B/C are overexpressed in primary melanoma compared to metastatic melanoma." (PMID 33441834, 2021).
non-small cell lung carcinoma (3 papers, 2021 to 2024). A group of at least three distinct histological types of lung cancer, including non-small cell squamous cell carcinoma, adenocarcinoma, and large cell carcinoma. "Non-parametric assessment of the correlations between clinicopathological factors and SRXN1 and KRT6A expression levels in 75 patients with non-small-cell lung cancer." (PMID 35071014, 2021). "Although KRT6A upregulation in non-small cell lung cancer (NSCLC) has been reported, the regulatory mechanism and functional role of KRT6A in NSCLC development have been less well investigated." (PMID 34235156, 2021).
ovarian carcinoma (3 papers, 2007 to 2021). A malignant neoplasm originating from the surface ovarian epithelium. "Decreased expression of KRT6A and S100A7 have been associated with breast, lung and ovarian cancer." (PMID 17543121, 2007). "KRT5 and KRT6 (KRT6A, KRT6B & KRT6C) gene expression was assessed in publically available serous ovarian cancer data sets, ovarian cancer cell lines and primary serous ovarian cancer cells." (PMID 28147318, 2017).
pancreatic ductal adenocarcinoma (3 papers, 2020 to 2024). An infiltrating adenocarcinoma that arises from the epithelial cells of the pancreas. "In contrast, a study on the immune microenvironment in pancreatic ductal adenocarcinoma showed that KRT6A could modulate the function of tumor-associated macrophages (TAMs), an important part of the leukocyte infiltrate, through other proteins and molecular pathways." (PMID 39000463, 2024). "KRT6A is differentially expressed in pancreatic duct adenocarcinoma (PDAC) and adjacent normal tissue (ANT), which can mediate tumor-associated macrophage subtypes in PDAC changes in β-catenin." (PMID 37505298, 2024).
pterygium (3 papers, 2009 to 2025). A wedge-shaped fibrovascular lesion arising from the bulbar conjunctiva and extending to the cornea. "For example, KRT6A expression is upregulated in pterygium, a benign overgrowth of BC, while KRT17 marks limbal SCs and regulates their stemness, differentiation, proliferation, and immune responses." (PMID 41439999, 2025). "Genes encoding for extracellular matrix, structural and adhesion molecules including wound healing related proteins, collagen subtypes, keratin 6A and fibronectin were significantly up-regulated in pterygium." (PMID 19272163, 2009). "Among those DE-mRNAs, matrix metallopeptidase 3(MMP-3), fibronectin 1 (FN1), tenascin C (TNC), LRRC15, KRT6A, COMP, AKR1B10, and MUC5AC were significantly upregulated, which was consistent with previous studies on pterygium." (PMID 36398070, 2022). "Immunofluorescence showed strong expression of keratin-6A in all layers, especially the superficial layers, of pterygium epithelium, but absent in the control, with up-regulation and nuclear accumulation of the cell adhesion molecule CD24 in the pterygium epithelium." (PMID 19272163, 2009).
cervical cancer (2 papers, 2012 to 2025). A primary or metastatic malignant neoplasm involving the cervix. "We performed a similar analysis on our RNA-seq analysis and identified several genes that are also implicated in cervical cancer and HPV infection, including Krt16 (up), Krt6a (up), Hmox1 (up), and Krt15 (down)." (PMID 41165329, 2025).
colon adenocarcinoma (2 papers, 2021 to 2023). "Interesting, after calculating the comprehensive signature of KRT6A and S100A2 in CRC tissues (including colon adenocarcinoma and rectum adenocarcinoma), we found that the signature score derived from KRT6A and S100A2 was higher in CRC tissues compared non-tumor tissues." (PMID 37647260, 2023).
esophageal cancer (2 papers, 2023). A primary or metastatic malignant neoplasm involving the esophagus. "Of the top 20 genes whose expression most correlated with ZNF750 expression in esophageal cancer, 10 were epidermal differentiation and keratinization-related genes, such as LYPD3, KRT6A, KRT16, and IVL." (PMID 37365152, 2023).
gastric cancer (2 papers, 2011 to 2023). A primary or metastatic malignant neoplasm involving the stomach. "Expression of KRT6A and PLAC1 was significantly changed by both SOX2 over-expression and knockdown, suggesting that SOX2 is the critical regulatory factor for these two genes in gastric cancer cells." (PMID 21304604, 2011).